IL13 (interleukin 13)
Diseases named in the same sentence as IL13 in open-access papers (continued):
Sharing a sentence is not in itself a finding about the gene and the disease.
liver fibrosis (continued). "We have provided evidence that TGM2 regulates the TGF-β1 of parasite origin and IL-13 of the host as well as documented the important role of TGM2 in liver fibrosis during Sj infection." (PMID 29321784, 2017). "Paeoniflorin has been shown to protect mice against Schistosoma japonicum egg-induced hepatic fibrosis by interfering with the IL-13 signaling molecule and decreasing the level of IL-13." (PMID 27525026, 2016). "IL‐13 secreted from natural‐killer T (NKT) cells 20 has been shown to progress liver fibrosis 21 in NAFLD." (PMID 27761360, 2016). "Th2 cytokines IL-4, IL-5 and IL-13 are dramatically increased in liver fibrosis with IL-13 being an indispensable mediator of fibrosis." (PMID 26771187, 2016). "IL-13 mediates hepatic stellate cell activation and the subsequent secretion of collagen contributes to the development of liver fibrosis." (PMID 26258681, 2015). "Taken together with our data, these findings suggest that IL-13 plays a role in the development of hepatic fibrosis after S. japonicum infection." (PMID 26258681, 2015). "More importantly, transferring M(IL-13) that were transduced with either miR-130a-3p mimics or miR-142-5p ASO into the CCL4-treated Ccr2−/− mice rendered much milder liver fibrosis compared with transferring the untransduced M(IL-13) cells." (PMID 26436920, 2015). "Expression of IL-13 was measured in S. japonicun-infected liver fibrosis tissue and normal liver tissue from uninfected controls by immunohistochemistry (IHC)." (PMID 26258681, 2015). "Beside TGF-β, IL-13 and Il-17 were recently demonstrated as another critical pro-fibrotic cytokines in liver fibrosis, for example, IL-13 can potently induce the synthesis of collagen I and other fibrotic markers directly in Schistosoma spp." (PMID 25649869, 2015). "We also confirmed IL-13 protein levels were up-regulated in S. japonicum-induced liver fibrosis tissues compared to normal liver tissues." (PMID 26258681, 2015). "Although the correlation between IL-13 and liver fibrosis in Sm has been found, more research is required for further assessment of the mechanisms by which IL-13 influences liver fibrogenesis." (PMID 25110399, 2014). "IL-13 is thought to be the key mediator of liver fibrosis in Sm, as antagonizing IL-13 or IL-13−/− mouse liver fibrosis was abrogated." (PMID 25110399, 2014). "Considering that IL-13 and tTG are involved in liver fibrosis after Sj infection, we tested the level change of IL-13 after CTM treatment." (PMID 25110399, 2014). "The important function of IL-13 and tTG in Sj liver fibrosis makes them potential drug targets in preventing liver fibrogenesis." (PMID 25110399, 2014). "In Schistosoma mansoni- (Sm-) infected mice, IL-13 mediated liver fibrosis as a promoter and sustainer." (PMID 25110399, 2014). "This pro-fibrotic property of the S. mansoni granuloma was used to identify that IL-13 was the dominant Th2 cytokine responsible for the development of liver fibrosis." (PMID 23596444, 2013). "To avoid hepatic fibrosis, we chose a low dose of IL-13 administration to achieve only three times higher serum levels than found in atherosclerotic mice." (PMID 23027612, 2012). "Human studies suggest a correlation between production of high levels of IL-13 and development of more advanced degree of liver fibrosis." (PMID 23320145, 2012). "The blockage of IL-13 and IL-4 receptors prevented granuloma development and liver fibrosis in mice." (PMID 23320145, 2012). "Many studies in experimental models have shown that IL-13 plays an important role in the development of liver fibrosis." (PMID 23320145, 2012). "In a study on porcine serum-induced liver fibrosis in rats, Interleukin 13 (IL-13) levels are positively correlated with hydroxyproline (Hyp) contents in the liver." (PMID 19695098, 2009).
liver fibrosis (continued). "Given that granuloma formation and hepatic fibrosis are highly dependent on IL-13, these data demonstrated that Retnla plays a major suppressive role in both acute and chronic Th2-driven pathological responses." (PMID 19381262, 2009). "The IL-13 receptor alpha 2 functions as a decoy receptor for IL-13, and studies conducted with IL-13Rα2−/− mice demonstrated that the decoy receptor inhibits the development of hepatic fibrosis in schistosomiasis." (PMID 18369473, 2008). "Furthermore, it has been supported that IL-33 promotes hepatic fibrosis through the activation and expansion of liver-resident innate lymphoid cells (ILCs), which produce IL-13 that activates HSCs, representing a newly described fibrogenic mechanism." (PMID 40794228, 2025). "Thus, variable IL-13 signaling to these 2 cell types determined pathogenesis of liver fibrosis and biliary hyperplasia." (PMID 38051583, 2024). "It thus remains unclear and to be evaluated whether this particular subgroup of IL-13-producing ILC3-like cells also occurs in the context of S. mansoni-induced liver fibrosis." (PMID 37629063, 2023). "On the other hand, NKT cells might promote the progression of hepatic fibrosis through production of the type 2 profibrotic cytokines IL-4 and IL-13." (PMID 37817226, 2023). "Inhibiting IL-13 activity with IL-13Rα2 can reduce liver fibrosis." (PMID 36743413, 2023). "Recent studies suggest that macrophages switched to the M1 phenotype exert pro-inflammatory as well as pro-fibrogenic roles in the pathogenesis of liver fibrosis, while macrophages polarized to M2 phenotype responding to the stimulation of IL-4 or IL-13 attenuate the progression of liver fibrosis." (PMID 37760020, 2023). "All these results suggest a rather close association between IL-13, MASH, and liver fibrosis." (PMID 37629063, 2023). "For example, the IL13 promoter polymorphism rs1800925 (not studied here) has previously been associated with both elevated IL-13 expression and an increase in liver fibrosis associated with S. japonicum infection." (PMID 35759449, 2022). "We previously revealed that CsTPs could promote the production of Th2 cytokines, including IL-13 and IL-4, both in vitro and in vivo, and ultimately resulted in the development of liver fibrosis." (PMID 36510325, 2022). "For example, in our results IL-13 has been associated with fibrosis in both the FIBSig and the M1 module, and indeed, it is already known to play a pivotal role in various fibrotic diseases, such as SSc, IPF and liver fibrosis." (PMID 36632136, 2022). "Previous research showed that eggs could strongly invoke Th2 response and IL-13, a Th2 cytokines, directly promoted severe liver fibrosis." (PMID 36618421, 2022). "Therefore, it is very important to select and study targets capable of blocking pro-inflammatory (IL-13, IL-17, and IL-33) or inducing anti-inflammatory interleukin (IL-10) in the complex process of liver fibrosis." (PMID 33841164, 2021). "The correlation of CCL3 with hepatic fibrosis may be related to the fact that this chemokine stimulates the production of IL-13, which is considered a pro-fibrotic cytokine." (PMID 33777015, 2021). "The levels of cytokines IL-13 and TGF-β were consistent with the development trend of liver fibrosis caused by S. japonicum or CCl4, suggesting that TGF-β and IL-13 were important factors that promoted the progress of liver fibrosis." (PMID 33117360, 2020). "While TGFβ has been established as an essential mediator of fibrosis, IL-13 is also recognized to play a role both in a TGFβ-dependent manner, as shown in the context of colitis but also through an independent mechanism, as demonstrated in liver fibrosis." (PMID 32079296, 2020). "IL-13 was reported that could promote liver fibrosis by activating HSCs through the protein kinase C pathway." (PMID 33117360, 2020). "Hepatic fibrosis was clearly reduced in 52-week-old Abcb4−/−/IL-13−/− mice (p = 0.002)." (PMID 32846954, 2020).
liver fibrosis (continued). "In addition, both TGF-β1/SMAD and IL-13/STAT6 pathways have been identified as major pathways that promote liver fibrosis in schistosomiasis by activating HSCs." (PMID 32944173, 2020). "In addition, direct interference with the type 2 cytokine IL-13 by IL-13 inhibitor sIL-13Rα2-Fc leads to significant reduction of hepatic fibrosis in a mouse model of S. mansoni infection." (PMID 31950032, 2019). "We did not use IL-13 or IL-33 knockout mice or neutralizing antibody to verify that IL-13 or IL-33 play a role in liver fibrosis during Sj infection as several publications have already reported that IL-13 and IL-33 mediate liver fibrosis during Schistosoma infection." (PMID 31200771, 2019). "IL-33, by inducing IL-13 production in ILC2s, has been shown to have seemingly disparate roles in promoting tissue repair and cholangiocyte proliferation in EHBDs while also exacerbating liver fibrosis." (PMID 31022195, 2019). "As IL-13 has already been identified as a driver of liver fibrosis, it remains unclear whether ILC2-derived AREG also influences disease progression." (PMID 30999584, 2019). "It was suggested that the concurrent pro-fibrotic effect of IL-33 might be mediated by induction of IL-13 expression in ILC2 as shown in murine models of hepatic fibrosis, in which ILC2-derived IL-13 activated HSC, the key drivers of hepatic fibrosis." (PMID 30213101, 2018). "Moreover, expression of Th1 or Th2 cytokines important for liver fibrosis, such as IL-6, IL-10, IL-13, and TNF-α, were also detected in our experiment." (PMID 29703259, 2018). "Th2 cytokines, mainly IL-4 and IL-13, had distinct roles in the regulation of liver fibrosis." (PMID 29505573, 2018). "Thus, by reducing IL-13 levels, WJMSCs is suggested to have anti-inflammatory or anti-fibrotic effects in this model of liver fibrosis." (PMID 26876222, 2016). "Further supporting a role for IL-13 in tissue fibrosis, experiments using soluble worm antigen preparation (SWAP) or soluble egg antigen (SEA) stimulated peripheral blood mononuclear cells (PBMC) showed that IL-13 was produced and subsequently facilitated liver fibrosis." (PMID 26258681, 2015). "For example, S. japonicum-infected mice develop liver fibrosis with higher IL-13 mRNA and a large amount of collagen deposition, which could be relieved by IL-13 blockader." (PMID 26258681, 2015). "St2−/−, Il13−/−, and Il4rα−/− mice are resistant to this treatment, strongly suggesting that the IL-33–IL-13 axis is important for the development of IL-33-induced liver fibrosis." (PMID 26549942, 2015). "Single nucleotide polymorphisms (SNPs) rs1800925 (IL13/-1112C>T) and rs20541 (IL13R130Q) were genotyped in 947 unrelated individuals (307 chronically infected, 339 late-stage with liver fibrosis, 301 uninfected controls) from a schistosomiasis-endemic area of Hubei province in China." (PMID 26258681, 2015). "However, transferring either monocytes or M(IL-13) into the Ccr2−/− mice recapitulated hepatic fibrosis, with M(IL-13) transfer at a later stage (between 3 to 5 weeks following the CCL4 challenge) showing the most prominent profibrogenic effects." (PMID 26436920, 2015). "However, only norUDCA treatment led to a reduced granuloma size with secondary beneficial effects on TH2-cytokine (IL-13 and -4) driven hepatic fibrosis." (PMID 25463533, 2015). "Thus, BSE-CD treatment attenuates S. japonicum egg-induced hepatic fibrosis independent from a decreased expression of IL-13 and TGF-β1." (PMID 24941000, 2014). "Importantly, we further demonstrate that the treatment of mice with Sj-induced liver fibrosis by using an inhibitor of the enzymatic activity of tTG inhibits the Sj-induced upregulation of IL-13 and alleviates liver fibrosis." (PMID 25110399, 2014). "tTG inhibition through CTM reduces IL-13 and then suppresses liver fibrosis." (PMID 25110399, 2014). "Therefore, we propose a model to illustrate the possible mechanisms linking tTG, IL-13, and liver fibrosis." (PMID 25110399, 2014).
liver fibrosis (continued). "Based on their important functions in liver fibrosis induced by Sj infection, IL-13 and tTG could be promising potential drug targets against schistosomiasis." (PMID 25110399, 2014). "Regression of liver fibrosis was also evidenced by histopathological, morphometric, and gelatin zymographic results, in addition to the reduction of three vital contributors to liver fibrosis in the model studied including alpha smooth muscle actin, collagen-I, and interleukin-13." (PMID 37440921, 2023). "Although IL-13 plays an important role in the induction of allergic responses and inflammation as anti-inflammatory cytokine, it is a critical pro-fibrotic factor in liver fibrosis associated with Schistosoma and non-Schistosoma infection." (PMID 33841164, 2021). "Moreover, blockade of IL-4 or IL-13 inhibits the effects of NKT cells on upregulating α-SMA in HSCs in vitro, suggesting that NKT cells promote liver fibrosis via Th2 cytokines in HBV-associated liver fibrosis." (PMID 32708044, 2020). "However, whether IL-21, as other profibrogenic cytokines such as TGF-β1 and IL-13 characterized by Smad signaling pathway, plays an important role in the development of hepatic fibrosis is worthy of further research." (PMID 29192177, 2017). "While hepatic fibrosis is impaired in S. mansoni-infected mice unable to signal through IL-4Rα (Il-4rα−/−), it is ablated in mice treated with soluble IL-13Rα2-Fc and also fails to develop in mice deficient in IL-13 (Il-13−/−)." (PMID 23596444, 2013). "Elevated levels of circulating IL-13 and increased expression of IL-13 receptor alpha 2 (IL-13Rα2) in the liver have been reported in individuals with MASH, with liver fibrosis mitigation observed upon targeting IL-13Rα2+ cells, including HSCs." (PMID 40370443, 2025). "Of note, IL-13 also functions synergistically with TGF-β to promote fibrosis and IL-13/ TGF-β blockade was more effective than single TGF-β blockade in alleviating hepatic fibrosis in NAFLD mice." (PMID 40794228, 2025). "Like PGD2-directed maneuvers, antagonism of cysteinyl leukotriene receptors CysLT1 by MK571 also promoted enhancement of TGF-β and IL-13, indicating a key down-regulatory role for endogenous LTC4 in schistosomiasis-induced liver fibrosis." (PMID 39173086, 2024). "Suppressing the pathological progression of liver fibrosis by inhibiting TGF-β1/SMAD and interleukin-13 (IL-13)/signal transducer and activator of transcription 6 (STAT6) pathwaysvia directly targeting semaphorin 4D." (PMID 39314046, 2024). "Activated ILC2 cells then produce IL-13, which in turn activates HSCs in an IL-4Rα- and STAT6-dependent manner to aggravate liver fibrosis." (PMID 33869241, 2021). "Chronic stimulation of anti‐inflammatory (IL‐4, IL‐10, IL‐13 and TGF‐β1) factors is related to liver fibrosis progression." (PMID 31755616, 2020). "Some reports showed that after egg deposition in the liver, pro-fibrotic factors, such as VEGF, IL-13, TGF-β, or IL-33, also increased and promoted the formation of liver fibrosis." (PMID 33330140, 2020). "IL-13 increased collagen production by activating STAT6 and promoted S. mansoni infection-induced liver fibrosis in a TGF-β-independent manner." (PMID 32708044, 2020). "We also provided evidence that TGM2 regulates TGF-β1 of Sj origin and IL-13 of the host and documented the important involvement of TGM2 in liver fibrosis during Sj infection in previous studies." (PMID 29321784, 2017). "In the liver fibrosis, the increased levels of IL5 lead to progress of tissue damage by regulating IL13 production and macrophage activation." (PMID 28288584, 2017). "C57Bl/6 mice fed HFD developed liver fibrosis and increased hepatic procollagen and TGF-β mRNA expression, and IL-33, IL-13 and TGF-β levels in liver homogenates, while BALB/c mice fed HFD had scarce collagen deposition in liver." (PMID 26218873, 2015). "IL-13 and -4 serum protein levels were determined since these cytokines have a regulatory importance in TH2 driven liver fibrosis." (PMID 25463533, 2015).
liver fibrosis (continued). "Both IL-13 and TGF-β1 are involved in the activation of “resting” HSCs and they are known to play an important role in promoting hepatic fibrosis in schistosomiasis." (PMID 24941000, 2014). "Profibrotic factors such as IL-1α and IL-1β that play a role in liver fibrosis development, and TNF-α which is an essential cofactor of IL-13 to induce the expression of IL-13Rα2, were upregulated." (PMID 24143891, 2013). "In contrast, Sja-miR-71a derived from theS. japonicum egg-released EVs was reported to suppress the pathological progression of hepatic fibrosis by inhibiting the TGF-β1/SMAD and IL-13/signal transducer and activator of transcription 6 (STAT6) pathwaysvia directly targeting semaphorin 4D." (PMID 39314046, 2024). "Furthermore, pro-fibrotic cytokines, such as IL-13 and TGF-β1, released during the immune response, can activate HSCs and drive hepatic fibrosis via the SMAD pathway." (PMID 39139565, 2024). "It has also been demonstrated that cytokines such as IL-13, transforming growth factor (TGF)-β1 and tumor necrosis factor (TNF)-α promote hepatic fibrosis, while cytokines such as interferon (IFN)-γ and IL-10 inhibit hepatic fibrosis." (PMID 38086792, 2023). "The global cytokine surveys of HSC-CM have demonstrated that TNF-α, agrin, PDGF, activin A, GM-CSF, IFN-γ, IL-1β, IL-4, IL-6, IL-10, IL-13, and TIMP-1, which subsequently induce acute inflammation and liver fibrosis, were elevated in aHSC-CM relative to the qHSC-CM." (PMID 36142683, 2022). "It has been reported that functional IL-13Rα2 was upregulated in activated hepatic stellate cells (HSCs) in NASH, and IL-13 cytotoxin-mediated killing of IL-13Rα2+ cells can ameliorate liver fibrosis in a rat model of NASH, indicating the involvement of the IL-13/IL-13Rα2 pathway in NASH." (PMID 36032141, 2022). "Although Th2 cells may play an anti-inflammatory part in NAFLD, it still promotes liver fibrosis in NAFLD, especially under the influence of IL-13." (PMID 36457551, 2022). "Meanwhile, liver fibrosis is alleviated in mice lacking ST2 or IL-13, however, transfusion of ILC2 restores fibrosis." (PMID 33869241, 2021). "Evidence suggests that upregulation of the serum cytokine levels of interleukin 13 (IL-13), IL-5, IL-4, and TGF-β may lead to hepatic fibrosis." (PMID 34869360, 2021). "Cytokine profiles in other studies have also shown an increased progression of IL-5 and IL-13 expression among patients experiencing severe hepatic fibrosis over an extended period of one year without treatment." (PMID 34281269, 2021). "Thus, critical roles for IL-33 in activation of Th2 immune responses via cytokines IL-4, IL-6 and IL-13 have been demonstrated in the pathogenesis of HSEC proliferation and liver fibrosis in mouse models." (PMID 32486265, 2020). "Sja-miR-71a suppresses liver fibrosis by Sema4D/TGF-β1 axis and Sema4D/IL-13 axis." (PMID 32944173, 2020). "Next, we verified whether Sja-miR-71a suppresses liver fibrosis through the Sema4D/TGF-β1 axis and Sema4D/IL-13 axis in HSCs." (PMID 32944173, 2020). "In the present study, we analyzed the effect of IL-13 on cholestasis and on the intestinal microbiome in Abcb4−/− mice and found that the absence of IL-13 improved cholestasis and hepatic fibrosis in Abcb4−/− mice." (PMID 32846954, 2020). "Thus, we conclude that Sja-miR-71a suppresses liver fibrosis by inhibiting the Sema4D/TGF-β1 and Sema4D/IL-13 axes." (PMID 32944173, 2020). "It was suggested in a mouse model that IL-13 activates liver fibrosis in a mechanism that is independent of TGF-β showing the importance of this cytokine in the potential management of fibrosis." (PMID 26771187, 2016). "Furthermore, IL13 knock-out mice infected with S. japonicum showed less eosinophil and smaller CD4+ T-driven granulomas and were protected from the development of liver fibrosis." (PMID 26258681, 2015).